XBP1 (X-box binding protein 1)
Diseases named in the same sentence as XBP1 in open-access papers (continued):
Sharing a sentence is not in itself a finding about the gene and the disease.
colon carcinoma (20 papers, 2015 to 2025). "The current study evaluated the role of XBP1 in TAMs associated with colon cancer." (PMID 34667145, 2021). "Although differences in the colon were less pronounced, we also noted colonic tumors in aged Atg16l1/Xbp1/Rnaseh2bΔIEC mice (20.0%), when compared to aged Xbp1/Rnaseh2bΔIEC mice (2.13%)." (PMID 41057521, 2025). "In the colon and small intestine of individuals with IBD and colon cancer, elevated XBP1 splicing, indicative of ER‐stress, is observed." (PMID 40953838, 2025). "Increased prevalence of small intestinal and colonic tumors resulted in decreased survival of Atg16l1/Xbp1/Rnaseh2bΔIEC mice." (PMID 41057521, 2025). "For example, the up-regulation of inositol-requiring enzyme 1α (IRE1α) and X-box binding protein 1 (XBP1) pathway is shown to cause drug resistance to 5-flurouracil through the expression of efflux transporters, ABCB1, ABCC1, and ABCG2 in colon cancer cells." (PMID 36015138, 2022). "XBP1 was recently reported to initiate FN1 expression in colon cancer cells and thus deserves further study as a possible link between hypoxia, UPR, and ECM remodeling in the context of EVT differentiation." (PMID 34540826, 2021). "Our results suggested that XBP1 in TAMs had potential as a novel therapeutic target in human colon cancer." (PMID 34667145, 2021). "Following our results, a transcriptomic analysis of colon cancer cells showed that rosemary polyphenols induced the activation of IRE1/XBP1 and PERK/ATF4 as a protective sensitization mechanism." (PMID 34836245, 2021). "In the intestine, activation of the UPR through the kinase PERK results in differentiation of intestinal epithelial stem cells and colon cancer stem cells, whereas deletion of XBP1 results in increased stemness and adenomagenesis." (PMID 31227689, 2019). "The proapoptosis signaling proteins CHOP and XBP-1 were also reduced in the presence of NAC in both colon cancer cells compared with the NAC and Andro treated cells." (PMID 28412728, 2017). "Other cancers, like liver and colon cancers, were also reported to be with activation of XBP1, however, the specific mechanisms were seldom explored." (PMID 26633383, 2015). "Additionally, XBP1 activation facilitates pro-tumor function of TAMs, thus accelerating the growth and metastasis of colon cancer, which has been verified in prior study." (PMID 38554175, 2024). "Knockout of XBP1 in TAMs significantly inhibited the progression and metastasis of colon cancer." (PMID 34667145, 2021). "XBP1 activation is detected in TAMs of colon cancer patients and AOM-DSS mouse model in our study." (PMID 34667145, 2021). "Moreover, Hif1α has also been shown to support colon cancer cell proliferation by interacting with spliced X-box-binding protein 1 (XBP1)." (PMID 32927611, 2020). "Finally, XBP1-s is negatively correlated with poor prognosis and low survival of pulmonary adenocarcinoma, colon carcinoma, and gallbladder cancer patients, further supporting the view that increased XBP1-s expression contributes to the acquisition of EMT phenotype and tumor metastasis." (PMID 35269888, 2022). "UPR has been found to be activated in most tumor samples originating from colon cancer biopsies, while the expression of UPR molecules such as BiP and PERK/eIF2 alpha and the XBP1 axis have been correlated with a poor prognosis." (PMID 34572447, 2021). "Because XBP1 and ATF6 have extensively overlapping sets of target genes, we set out to investigate both XBP1 and ATF6 signaling in colon cancer cells, and investigate the crosstalk of these branches with PERK- eIF2α20,29." (PMID 31227689, 2019). "Besides, the cleaved XBP1 mRNA was also higher expressed than that of normal tissue, indicating that UPR was constitutively activated in colon cancer tissue." (PMID 36147440, 2022). "To determine whether TDA activates endoplasmic reticulum stress in colon cancer cells, we examined the expression of PERK, IRE1α, XBP1 and HSPA5 using Western blot." (PMID 34070303, 2021).
colon carcinoma (continued). "Thus, enforced expression of XBP1(s) and ATF61–373 in colon cancer cells results in decrease in stemness and proliferation, not attributable to doxycycline." (PMID 31227689, 2019).
glioma (20 papers, 2010 to 2025). A benign or malignant brain and spinal cord tumor that arises from glial cells (astrocytes, oligodendrocytes, ependymal cells). "The PPI showed that VEGFA and XBP1 are key genes linked to HIF-1α and that co-expression affected glioma prognosis." (PMID 40621799, 2025). "Further analysis indicated that S4 promotes calreticulin exposure and the release of HMGB1 and HSP70/90, thereby activating the PERK-eIF2α and IRE1α-XBP1 pathways and facilitating DAMP release linked to ICD in glioma cells through the ER stress pathway." (PMID 39184045, 2024). "We observed the elevated eIF2a phosphorylation and increased XBP1 levels, both markers of ER stress, in S4-treated glioma cells." (PMID 37386564, 2023). "Two enhanced signaling pathways, PERK-eIF2a and IRE1a-XBP1, were also identified in glioma xenografts in mice following radiotherapy-induced immunogenic cell death." (PMID 37376060, 2023). "Glioma strongly expresses PERK, ATF4, ATF6, IRE1, and XBP1, and is associated with the malignant phenotype and poor prognosis." (PMID 33920356, 2021). "In glioma cells, ER stress triggered by different drug treatments increases p-eIF2α in conjunction with elevated expression of other ER stress transducers (i.e. p-ERK, ATF6, p-IRE-1, GRP78, CHOP, XBP-1) enhancing glioma cell death." (PMID 31795417, 2019). "In our analysis of this data set, we identified a 1.4- to 1.9- fold elevation (p<0.001) of BiP/GRP78, GRP94, and XBP-1 message levels in gliomas of the poorer prognostic subtypes (mesenchymal and proliferative) relative to the pronerual group." (PMID 24039668, 2013). "If the gene expression data were sorted by WHO grade, again the levels of GRP78/BiP, GRP94, and XBP-1 were significantly elevated in grade IV gliomas (GBMs, with necrosis) compared to the lower grade III tumors." (PMID 24039668, 2013). "Following an acute 4 hour treatment with the reducing agent DTT, all glioma lines demonstrated a marked induction of XBP-1, BiP/GRP78, and CHOP mRNAs, while maintaining steady levels of GAPDH message." (PMID 24039668, 2013). "We have observed that 2OHOA treatments induced augments in the expression of important ER stress/UPR markers, such as phosphorylated eIF2α, IRE1α, CHOP, ATF4 and the spliced form of XBP1 in human glioma cells." (PMID 23133576, 2012). "Both VEGFA and XBP1 expression increased significantly with glioma pathological grade." (PMID 40621799, 2025). "Notably, combined high expression of XBP1 and VEGFA was significantly associated with poor glioma prognosis." (PMID 40621799, 2025). "Similarly, silencing XBP1 reduces glioma cell viability by inhibiting HK2 expression, thereby regulating glycolysis." (PMID 39273011, 2024). "The immune infiltration analysis further indicated that M0 macrophages may participate in the regulation of the prognosis of VEGFA-XBP1.Hypoxia-induced ferroptosis modulation emerges as a prognostic factor in gliomas, with XBP1 and VEGFA representing druggable nodes for novel combination therapies." (PMID 40621799, 2025). "Furthermore, targeting XBP1 enhances sensitivity of glioma cells to oxidative stress." (PMID 36768338, 2023). "We first assessed whether XBP-1(S) bound to any of the five potential sites in the rat promoter in response to ER stress using a chromatin immunoprecipitation (ChIP) assay, since the C6 rat glioma was used for both the mRNA stability and transcription assays." (PMID 20824063, 2010). "The results indicated that the combination treatment of curcumin and IR induced immunogenic cell death of glioma cells through ER stress PERK-eIF2α and IRE1α-XBP1 signaling pathways." (PMID 36238646, 2022). "And, the mRNA levels of ATF-4, XBP-1 (s), and CHOP were increased upon C18-ceramide addition in U251 and A172 glioma cells." (PMID 29262618, 2017). "We also verified these results using qRT-PCR analysis; the mRNA levels of ATF-4, XBP-1 (s), and CHOP obviously increased in U251 and A172 glioma cells in which CERS1 was overexpressed." (PMID 29262618, 2017).
glioma (continued). "By Western blot, the protein levels of ATF-4, XBP-1 (s), and CHOP increased in U251 and A172 glioma cells in which CERS1 was overexpressed." (PMID 29262618, 2017). "The protein expression of UPR effectors (ATF4, XBP-1, CHOP/GADD153) is also increased in glioma tumors, indicating that their enhanced transcription indeed leads to increased protein levels." (PMID 24039668, 2013). "Levels of key UPR transcripts XBP-1, CHOP, ATF4, and ATF6 were only nominally detected in normal brain and unstressed U87 glioma cells, as reported by other studies." (PMID 24039668, 2013). "While the mechanism by which XBP1, VEGFA and immune cells function remains unclear, XBP1 may present a new target for use in combination with VEGFA to treat glioma." (PMID 40621799, 2025). "Ionizing radiation-induced normoxic or hypoxic glioma immunogenic cell death could be further enhanced by curcumin through activating the ER stress PERK-eIF2α and IRE1α-XBP1 signaling pathways." (PMID 36238646, 2022). "This is again reflected in immunohistochemistry of glioma xenograft tumors; high levels of CHOP and ATF4 (driven by the PERK arm of the UPR) are evident compared to normal brain, as are those of XBP-1 (where we cannot distinguish between spliced and unspliced versions with this antibody)." (PMID 24039668, 2013). "RAC1 expression has previously been linked to transcription factor expression in glioma, and while the RNAseq data presented did not link ATF4 and XBP1 to RAC1 expression, the association may depend on cell type and genetic background." (PMID 29329780, 2018). "Interestingly, spliced XBP-1 was also detected in U87 glioma cells in the absence of TG treatment, indicating that these fast dividing cells may experience basal ER stress and activation of a mild UPR." (PMID 23335989, 2013). "As target genes of three branches, DDIT3 (CHOP) and DNAJB9 (IRE1α-XBP1), but not SEL1L (ATF6) were obviously upregulated in glioma cells after treatment of S4, which declared ATF6 was not the main activated branch." (PMID 37386564, 2023).
atherosclerosis (18 papers, 2012 to 2025). A disease characterized by the build-up of fatty material and calcium deposition in the arterial wall resulting in partial or complete occlusion of the arterial lumen. "Effects of IREα/XBP1 or ER stress modulators in experimental atherosclerosis and associated disease models." (PMID 37008067, 2023). "The polymorphism of the XBP1 (−116C/G) promoter was investigated in relation to ischemic stroke, atherosclerosis, and hyperhomocysteinemia in human patients, and the XBP1 (−116 G/G) genotype was found to be a risk factor for pediatric ischemic stroke." (PMID 35783104, 2022). "Compared to the NC group, the HFD group showed enrichment of pathways associated with ferroptosis, chemokine signaling, NOD-like receptor signaling, lipid metabolism, and atherosclerosis, with XBP1 identified as a key regulatory molecule." (PMID 40413726, 2025). "The main purpose of this review is to elucidate the role of ER stress in atherosclerosis from the perspective of XBP1." (PMID 37008067, 2023). "Convincing studies have implied an essential role of XBP1 splicing during atherosclerosis and post injury neointima formation 9-11." (PMID 35173538, 2022). "NOX generated ROS also impacts on XBP1 splicing (X-box-binding protein 1), a key protein that promotes EC apoptosis and atherosclerosis formation." (PMID 31428618, 2019). "The regulated miR-135a-5p/XBP1 axis by knockdown of the long non-coding RNA LINC00299 could suppress oxidized low-density lipoprotein-induced T/G human aortic VSMC injury in atherosclerosis." (PMID 38027164, 2023). "XBP1 regulates the autophagy signaling pathway through Beclin-1 transcription, and sustained activation of XBP1 leads to endothelial cell apoptosis and promotes the development of atherosclerosis." (PMID 31320543, 2019). "Notably, the spliced XBP1 product, X26nt, was elevated in atherosclerosis." (PMID 40856260, 2025). "Indeed, XBP1, a key modulator of unfolded protein response, has been demonstrated to play an important role in the regulation of lipid metabolism and angiogenesis and the inhibition of this pathway alleviates atherosclerosis." (PMID 37060905, 2023). "As observed in human atherosclerosis patients, the ER stress markers KDEL and XBP-1 are increased compared with unaffected controls." (PMID 34440686, 2021). "Furthermore, X-Box binding protein 1 (XBP1), as a transcription factor, plays a crucial role in atherosclerosis by regulating the inflammatory response." (PMID 39742258, 2024). "In a disturbed flow-induced atherosclerosis mouse model, UDCA effectively reduced ER stress, evidenced by decreased expression of XBP1 and CHOP in ECs, and it inhibited the inflammatory response and apoptosis of ECs caused by disturbed flow, thus suppressing the formation of atherosclerotic plaques." (PMID 32963706, 2020). "In a mouse model of disturbed flow-induced atherosclerosis, UDCA was found to inhibit the formation of atherosclerotic plaques by inhibiting ER stress and attenuating inflammatory responses, as evidenced by decreased expression of XBP1 and CHOP and reduced adhesion molecule levels in ECs." (PMID 32963706, 2020). "Recently, a study of atherosclerosis showed that laminar flow protected ER stress-induced cleaved forms of PARP-1 and caspase-3 and inhibited the ER stress-induced p-eIF2α, ATF4, CHOP, spliced XBP-1, ATF6, and JNK pathways to protect endothelial cells from apoptosis." (PMID 31506423, 2019).
atherosclerosis (continued). "Additionally, while the overlap of BLIMP-1 and XBP-1 functions is restricted to the unfolded protein response, BLIMP-1 serves at the upstream of XBP-1 and uniquely regulates mTOR activity and plasma cell size, and therefore might have additional effects on the B cell population in atherosclerosis." (PMID 33572939, 2021).
enteritis (18 papers, 2015 to 2026). Inflammation of the small intestine. "It was demonstrated that XBP1 deletion in intestinal epithelial cells (IECs) causes spontaneous enteritis and enhanced vulnerability to produce colitis as a result of both Paneth cell insufficiency and IEC hyperactive responses to the IBD-inducing agents TNF-α and flagellin." (PMID 38592680, 2024). "Deletion of XBP1 in intestinal epithelial cells causes spontaneous enteritis." (PMID 36688692, 2023). "Also, induction of ER stress in intestinal epithelium through tissue (and cell type)-specific disruption of XBP1 results in spontaneous enteritis due to inability of XBP1-deficient IECs to properly generate antimicrobial activity and respond appropriately to inflammatory signals in the local milieu." (PMID 40359212, 2025). "Experimental studies point towards ER stress activation as a new pathway driving intestinal inflammation, as demonstrated by XBP1 deletion in intestinal epithelial cells leading to activation of ER stress and spontaneous enteritis." (PMID 31557250, 2019). "Genetic XBP1 defects can lead to spontaneous enteritis and imbalanced production of cytokines, including NF-κB and other proinflammatory cytokines." (PMID 28928666, 2017). "Specifically, deletion or downregulation of XBP1 leads to spontaneous enteritis and results in imbalanced secretion of NF-κB and other proinflammatory cytokines." (PMID 28928666, 2017). "In addition, we observed increased small intestinal enteritis score in Atg16l1/Xbp1/Rnaseh2bΔIEC, compared to Xbp1/Rnaseh2bΔIEC." (PMID 41057521, 2025). "Conditional deletion of intestinal ER stress-marker Xbp1 leads to a spontaneous enteritis in mice." (PMID 38218976, 2024). "These mice undergo spontaneous enteritis, implicating Xbp1 in initiating intestinal inflammation." (PMID 29701691, 2018). "Interestingly, Xbp1 deletion specifically in Paneth cells resulted in spontaneous enteritis similar to mice in which Xbp1 was deleted in all intestinal epithelial cells." (PMID 29701691, 2018). "This study confirmed the effect of DSS on the expression of autophagy-related 16-like 1 (ATG16L1) and X-box binding protein-1 (XBP1), genes used to evaluate the innate immune system, including DEFA5, in enteritis models." (PMID 39329151, 2024).